CD47 (CD47 molecule)
Diseases named in the same sentence as CD47 in open-access papers (continued):
Sharing a sentence is not in itself a finding about the gene and the disease.
tumor (continued). "Our results lend support for continued evaluation of the potentially multi-therapeutic benefits of targeting CD47 as a form of tumour immuno-therapy." (PMID 29748606, 2018). "When expressed by tumor cells, CD47 can bind SIRPα on myeloid cells, leading to suppression of tumor cell phagocytosis and other innate immune functions." (PMID 30133535, 2018). "CD47 expressed by tumor cells interact with SIRPα transmitting a “don't eat me” signal to macrophages to avoid being eliminated." (PMID 30525058, 2018). "Blockade of the CD47-SIRPα interaction enhances ADCP of tumor cells, demonstrating that if unchecked, CD47 expression can protect tumor cells from macrophage phagocytosis." (PMID 30133535, 2018). "CD47 upregulation in solid and hematological cancers is correlated with poor clinical prognosis, almost certainly by allowing tumor cells to escape immune surveillance." (PMID 30400822, 2018). "Previous studies have relied upon in vitro differentiated macrophages and DCs to demonstrate that in response to CD47 blockade these cells process tumor antigen and present them for priming of cytotoxic T cells." (PMID 30133535, 2018). "A similar decrease in CD8- DCs was previously reported in non-tumor bearing mice treated with antibodies blocking the CD47-SIRPα interaction." (PMID 30133535, 2018). "c-Myc is a universal amplifier of expressed genes in lymphocytes, stem cells and tumor cells, and c-Myc regulates several CD47-dependent metabolic programs in Jurkat T cells that are consistent with changes we observed in NK cells." (PMID 30643501, 2018). "Used in combination with radiation, CD47 inhibition has been shown to improve tumor radiosensitivity." (PMID 30854331, 2018). "We observed that tumor-directed blockade of CD47 enhances tumor antigen cross-presentation and CD8+ T cell activation in vitro." (PMID 31544856, 2018). "The 10 mg/kg dose resulted in 80 percent CD47 occupancy on splenic T cells twenty-four hours post-dose, while only 21 and 43 percent occupancy was observed for tumor cells and T cells, respectively, in the tumor compartment." (PMID 30133535, 2018). "Because ALX148 binds murine CD47 with high affinity, effects on antitumor efficacy and immune responses were evaluated in syngeneic murine tumor models." (PMID 30133535, 2018). "Antibodies blocking CD47 have been investigated in multiple tumor types to help promote macrophage tumor phagocytosis with efficacy observed in numerous preclinical models, including GBM." (PMID 30854331, 2018). "Blockade of CD47 increases phagocytosis of tumor cells and stimulates macrophage-mediated tumor elimination in various human xenograft tumor models." (PMID 31544856, 2018). "When delivered with the same dose and by the same route, FusOn-CD47-Luc showed a moderate but statistically significant impact on slowing down tumor growth." (PMID 30349648, 2018). "The CD47 blocking antibodies have been found to decrease tumor size and metastasis in several pre-clinical studies as well as initiate an antitumor cytotoxic T cell immune response." (PMID 30463284, 2018). "Our results suggested that applying anti-CD47 mAb during the “watchful waiting” period is expected to eliminate these tumor seeding cells and further benefit the patients' long term prognosis." (PMID 28380460, 2017). "Supporting this, conditional deletion of Ifnar 1 in CD11c+ cells markedly reduced the therapeutic effect of CD47 blockade on tumor growth." (PMID 28077173, 2017). "In several pre-clinical studies, CD47 monoclonal antibody (mAb) treatment has shown impressive anti-tumor effects in xenograft cancer models." (PMID 28380460, 2017). "Our results hence indicate that the rewiring of CD47 signaling in macrophages by SIRPα Shp2-iSNAP can promote the antibody-mediated tumor cell phagocytosis." (PMID 28883531, 2017). "Blocking the interaction between CD47 on tumor cells and SIRPα on macrophages has been shown to induce antitumor responses." (PMID 27283989, 2017).
tumor (continued). "This information suggests that even though CD47 gene expression can be regulated in a broader range of cancer cells by one common enhancer, certain constituent enhancers located within CD47 SEs seem to have a more tumour type-specific regulatory activity." (PMID 28378740, 2017). "We evaluated CD47 expression on dissociated primary lung tumor cells (tumor cells) and matched adjacent normal cells (normal cells) from human patients by flow cytometry (FACS)." (PMID 28484448, 2017). "Given that blockade of CD47-SIRPα signaling axis has (and continues to) demonstrate success in more pre-clinical tumor models, more entries into clinical trials involving the CD47-SIRPα axis are anticipated." (PMID 28077173, 2017). "Given the ubiquitous expression of CD47 on normal cells, tumor-specific delivery of CD47 blockade would generate better anti-tumor effect with fewer side effects than systemic administration." (PMID 28077173, 2017). "Importantly, the observed delays in tumor growth in resected animals treated with anti-CD47 mAb treatment were associated with a significantly improved outcome compared to resected animals treated with IgG control antibody (81.5 days vs 69.0 days, anti-CD47 vs IgG control; P = 0.0007)." (PMID 28076333, 2017). "CD47 is a marker on tumor cells, which protects from phagocytosis and is upregulated in many cancers." (PMID 28470464, 2017). "In syngeneic immunocompetent mouse models, mouse anti-CD47 blockade shows impressive anti-tumor effect especially upon intratumoral delivery." (PMID 28077173, 2017). "Tumor volume as a function of time increased similarly for treatment with anti-CD47 or control IgG antibody, as for the control group, and anti-CD47 treated animals became symptomatic within 6 weeks of implantation just as controls." (PMID 28076333, 2017). "We suggest that the resulting licMAB blocks the CD47-SIRPα interaction at the site of tumor antigen-expressing cells." (PMID 28061465, 2017). "Anti-CD47 mAb relative to IgG inhibited tumor growth in combination with resection, and differences in tumor volume compared to controls were statistically significant at weeks 7 (P = 0.0064), 8 (P = 0.0169) and 9 (P = 0.0062)." (PMID 28076333, 2017). "It was found that chemotherapy administered after anti-CD47 therapy has a detrimental effect on the development of beneficial anti-tumor memory immune responses." (PMID 28077173, 2017). "In conclusion, targeting CD47 in a monospecific antibody format is challenging as anti-tumor activity and tolerability of anti-CD47 mAbs are dependent on Fc effector function." (PMID 28234345, 2017). "Calreticulin can interact with LDL-receptor-related protein 1 on macrophages and is required for the phagocytosis of tumor cell lines, whose function is to neutralize CD47–SIRPα interaction." (PMID 28484448, 2017). "CD47 expression levels were lower in the turboRFP-NFKB1 shRNA MCF7 tumours than in tumours formed by the control MCF7 cells." (PMID 28378740, 2017). "For this reason, IgG-based bispecific antibodies were created to block CD47 combining tumor targeting." (PMID 28469973, 2017). "The tumor size and weight from the CD47-CAR-T cell-treated group were significantly less (p < 0.05) than from the control 1× PBS and CD24-CAR-T cell groups." (PMID 29065481, 2017). "We now show new data indicating that anti-estrogen therapy regulates CD47 expression and implicates its ligand, thrombospondin-1, in regulation of tumor macrophage infiltration." (PMID 28815041, 2017). "ATP5B and PNPLA2 PEDF receptors on macrophages and CD47 on tumor cells were respectively up- and down-regulated by PEDF." (PMID 28403150, 2017). "The CD47 pathway was successfully blocked with mouse antibodies, humanized antibodies or completely human antibodies against CD47 antigen that resulted in blocking tumor growth using cancer cell line and patient-derived xenograft mouse models." (PMID 29065481, 2017).
tumor (continued). "In a previous study, anti-CD47 antibody elicited a profound effect in the treatment of solid tumors including GBM; however, efficacy of anti-CD47 blockade was highly correlated with tumor size." (PMID 28076333, 2017). "In this study we report the development of licMABs, novel therapeutic agents that combine specific tumor antigen binding, Fc-mediated immune cell recruitment and activation, and simultaneous disruption of the CD47-SIRPα axis." (PMID 28061465, 2017). "In our study, CD54 was found to be significantly upregulated in the debulking tumor + CD47 antibody group." (PMID 28076333, 2017). "As our iSNAPs can rewire the anti-phagocytic CD47-SIRPα signaling toward pro-phagocytic actions, CD47 on tumor cells actually promotes phagocytosis of engineered macrophages." (PMID 28883531, 2017). "In our study, anti-human CD47 antibody remarkably enhanced the phagocytosis of lung CSCs from the cell line and primary tumors in vitro and significantly inhibited tumor growth in the two lung CSCs xenotransplantation models." (PMID 28484448, 2017). "Using a syngeneic breast cancer model, mouse anti-CD47 antibody treatment resulted in a statistically significant decrease in final tumor weight compared to IgG isotype control." (PMID 28100392, 2017). "Anti-CD47 treatment was reported to increase macrophage phagocytosis, decrease tumor weight, and inhibit spontaneous metastasis in a osteosarcoma xenograft model." (PMID 28100392, 2017). "In summary, these results suggest that licMABs interfere with the CD47-SIRPα axis upon tumor antigen binding, thus blocking the inhibitory signal in macrophages and enhancing specific phagocytosis of target AML cell lines." (PMID 28061465, 2017). "CD47, expressed on a variety of tumor cells, confers immune resistance by delivering an inhibitory “don't eat me” signal to phagocytic cells via its myeloid-specific receptor SIRPα." (PMID 28061465, 2017). "Most of the literature describes CD47 as a marker of “self” that promotes tumor escape from macrophage immunosurveillance." (PMID 28815041, 2017). "PD-1/PD-L1 blockade alone or combined with anti-CD47 therapy in vivo increased macrophage phagocytosis but decreased tumor growth and increased survival of mice." (PMID 29255458, 2017). "Our recently published data implicate GRP78-mediated CD47 regulation as a possible molecular driver to promote anti-tumor macrophage recruitment." (PMID 28815041, 2017). "Third, it is also possible that the chemotherapy preconditions the tumor microenvironment with more infiltrating inflammatory cells, allowing anti-CD47 blockade to work." (PMID 28077173, 2017). "CD47-CAR-T cells significantly decreased BxPC3 xenograft tumor growth compared with controls, p < 0.05." (PMID 29065481, 2017). "CD47 is a cell surface antigen that is often overexpressed in tumor samples and plays multiple roles in tumor growth, metastasis and immunoregulation." (PMID 29065481, 2017). "Along similar lines, disruption of the CD47-SIRPα axis has been shown to synergize with the Fc-mediated pro-phagocytic stimulus of a mAb targeting a tumor antigen, such as rituximab, an antiCD20 mAb." (PMID 28061465, 2017). "Taken together, these data suggest that CD47 signaling in the tumor not only regulates phagocytic activity, but also mediates tumoral infiltration of macrophages." (PMID 28815041, 2017). "PEDF receptors (ATP5B, PNPLA2, and LRP6) and CD47 mRNA and protein expression were quantified in macrophages and tumor cells by quantitative RT-PCR, western blot, immunofluorescence and flow cytometry." (PMID 28403150, 2017). "The results indicated that numbers of macrophages in the tumor tissues in anti-CD47-treated mice were significantly higher compared to the IgG1 isotype-treated control mice." (PMID 28484448, 2017).
tumor (continued). "We recently demonstrated that targeting the unfolded protein response (UPR) protein GRP78 down-regulates CD47 expression, resulting in increased tumor macrophage infiltration and inhibited resistance to anti-estrogen therapy." (PMID 28815041, 2017). "Here, a surgical debulking GBM xenograft model was developed in nude rats, and was used in combination with CD47 blocking immunotherapy, a novel treatment strategy that triggers phagocytosis of tumor cells by macrophages in diverse cancer types including GBM." (PMID 28076333, 2017). "We found that TSP1 production in tumors from CD47-deficient mice was significantly reduced compared to those in WT mice, likely due to markedly reduced HIF-1A, VEGF production and hypoxia-induced tumor necrosis." (PMID 27283989, 2017). "The success of combination treatment including surgery and CD47 blocking immunotherapy is dependent on expression of CD47 in tumor cells." (PMID 28076333, 2017). "This raises a fascinating scenario that upon anti-CD47 treatment, DNA is released from tumor cells and taken up by DCs, resulting in the activation of STING and the production of type I IFN, which activates DCs for antigen cross-presentation." (PMID 28077173, 2017). "Given the important inhibitory function of CD47 in phagocytosis of tumor cells, it has been extensively investigated as a potential target for tumor therapy." (PMID 28077173, 2017). "Most work initially concluded that the therapeutic effects of anti-human CD47 were dependent on the direct killing of the tumor by phagocytes." (PMID 28077173, 2017). "A previous study showed that an anti-CD47 mAb treatment significantly reduced the tumor load in various types of malignant diseases." (PMID 28380460, 2017). "Anti-CD47 antibody treatment decreased the tumor burden in these mice and significantly prolonged survival compared to control IgG1." (PMID 28484448, 2017). "This study is the first to demonstrate that CD47 blockade using SIRPαFc triggers phagocytosis of tumor cells by a broad spectrum of human macrophages as well as mouse TAMs isolated ex vivo." (PMID 29084248, 2017). "Deregulation of CD47 and CD274is in concordance with an earlier report of 263 TCGA tumours but remaining 11 immuno-regulatory genes showed heterogeneous deregulation." (PMID 28886030, 2017). "Similar to shRNA knockdown, anti-CD47 mAb increased in vitro macrophage phagocytosis, decreased tumor initiation in vivo, and most importantly, promoted macrophage infiltration into xenograft tumors." (PMID 28380460, 2017). "CINC-3 is a strong chemotactic factor for neutrophils and was found to be downregulated in the debulking tumor + CD47 antibody group." (PMID 28076333, 2017). "In all 11 patients, CD47 expression levels were significantly higher in the tumor tissues than the normal tissues with an approximate 4.9-fold increase in intensity." (PMID 28380460, 2017). "Particularly, a study has shown that CSCs have increased CD47 expression to protect themselves from immune-mediated elimination during conventional anti-tumor therapies." (PMID 28077173, 2017). "For example, blockade of CD47 expression on tumor cells, driving macrophage T cell and dendritic cell activation leads to tumor cell killing." (PMID 28638379, 2017). "We argue that CD47 is a checkpoint molecule for both innate and adaptive immunity for tumor evasion and is thus a promising target for cancer immunotherapy." (PMID 28077173, 2017). "Increased phagocytosis of tumor cells mediated by targeting CD47 was inhibited by CALR blockade and its interaction with low density lipoprotein receptor-related protein-1 (LRP1)." (PMID 28815041, 2017). "We developed a protocol for surgical resection of GBM in nude rats which parallels the clinical course observed in human patients, tumor debulking followed by tumor relapse, and the model was used specifically to test combination therapy with anti-CD47 mAb." (PMID 28076333, 2017).
tumor (continued). "Our findings qualify licMABs as a promising therapeutic approach to confine the benefit of disrupting the CD47-SIRPα axis to tumor antigen-expressing cells." (PMID 28061465, 2017). "In contrast, chemotherapy administered before anti-CD47 therapy not only synergized with anti-CD47 for tumor control but also preserved the host memory response against relapsing tumors." (PMID 28077173, 2017). "Compared to CD44- tumor cell subsets, higher CD47 expression was observed in CD44+ tumor stem cells." (PMID 29029546, 2017). "All of these experimental results demonstrate that T cells are essential for anti-mouse CD47-mediated tumor regression." (PMID 28077173, 2017). "Inversely, the “don’t eat me” CD47 signal, expressed on the tumor cell surface was repressed by PEDF." (PMID 28403150, 2017). "Treatment with anti-human CD47 antibody inhibited CSC-initiated tumor growth as evidenced by bioluminescence imaging." (PMID 28484448, 2017). "Recently, researchers have used antibodies to block CD47 resulting in diminished tumor size in epithelial tumor models." (PMID 29187162, 2017). "The authors demonstrated that intravenous delivery of CD47 siRNA blocked melanoma tumor growth and lung metastases." (PMID 29065481, 2017). "CD47 was found to be universally expressed in human cancers where helps to prevent phagocytic elimination of tumor cells." (PMID 29387053, 2017). "We apply these iSNAPs to rewire the ‘don’t eat me’ CD47 signaling, leading to significantly enhanced phagocytic capabilities of engineered macrophages against tumor cells." (PMID 28883531, 2017). "The antitumor efficacy of mAbs and macrophages can be hindered by high expression of anti-phagocytic CD47 on tumor cells." (PMID 28883531, 2017). "Blockade of the CD47:SIRP-α axis between tumor cells and macrophages increases tumor cell phagocytosis in both solid tumors and hematological malignancies." (PMID 28804638, 2017). "Reducing cell surface CD47 expression promotes macrophage recognition and phagocytosis, suggesting that targeting tumor epithelial GRP78 is a necessary component to promote an anti-tumor immune response." (PMID 29113324, 2017). "There were some reports on CD47 siRNA that down-regulated CD47 and blocked tumor growth and also other reports demonstrated CD47-SIRP-alpha-independent pathways that blocked tumorigenesis such as interaction with thrombospondin, TSP-1, VEGFR-2 or EGFR." (PMID 29065481, 2017). "Binding of CD47 with SIRPα on macrophages and DCs conveys a “don't eat me” signal and accordingly, the blockage of CD47-SIRPα binding induces tumor regression by activating macrophages and DCs." (PMID 27283989, 2017). "We also designed humanized CD47 ScFv and showed its binding to human CD47 antigen by both ELISA and IHC staining using human tumor samples." (PMID 29065481, 2017). "Blockade of CD47 signalling via targeted monoclonal antibodies enables macrophage to phagocytose vulnerable tumour cells that were previously protected from immune surveillance." (PMID 28886030, 2017). "Expression of CD47 contributes to tumor progression by enabling AML cells to evade phagocytosis and is consequently correlated with a poor prognosis." (PMID 28061465, 2017). "The key goal of the engineered licMABs is to inhibit the CD47-SIRPα signaling pathway and thus increase the phagocytosis of tumor antigen-expressing cells." (PMID 28061465, 2017). "Anti-CD47 antibody therapy represents an alternative avenue to promote a pro-inflammatory environment that will enhance the body’s anti-tumor response." (PMID 27092773, 2016). "Tumor cells can evade phagocytosis by upregulating the “don’t eat me” signal CD47, and this evasion can be abrogated with anti-CD47 antibodies, which allow tumor cells to be engulfed and killed." (PMID 27185172, 2016).